ACSBG1 (acyl-CoA synthetase bubblegum family member 1)
Description:
Catalyzes the conversion of fatty acids such as long-chain and very long-chain fatty acids to their active form acyl-CoAs for both synthesis of cellular lipids, and degradation via beta-oxidation. Can activate diverse saturated, monosaturated and polyunsaturated fatty acids.
Synonyms: hBG1; hsBG; BGM; KIAA0631; LPD; FLJ30320; MGC14352; BG1; BG; GR-LACS
Tractability: Antibody: UniProt places it where antibodies can reach, with high confidence; its Gene Ontology location is reachable by antibodies, with high confidence. PROTAC: its protein half-life has been measured.
Gene: Protein-coding gene on chromosome 15 (78,167,468 to 78,245,688, reverse strand). Ensembl gene ENSG00000103740.
Subcellular location: Cytoplasm; Cytoplasmic vesicle; Microsome; Endoplasmic reticulum; Cell membrane
Subcellular location (Human Protein Atlas): Vesicles
Pathways (Reactome):
Metabolism: Synthesis of very long-chain fatty acyl-CoAs
Gene Ontology:
Molecular function: long-chain fatty acid-CoA ligase activity; very long-chain fatty acid-CoA ligase activity
Biological process: long-chain fatty acid metabolic process; very long-chain fatty acid metabolic process; long-chain fatty acid biosynthetic process; long-chain fatty-acyl-CoA biosynthetic process; myelination
Cellular component: cytoplasm; endoplasmic reticulum; plasma membrane; cytosol; cytoplasmic vesicle
Genetic constraint (gnomAD): Loss-of-function variants: 39 observed, 85.75 expected, observed/expected ratio (o/e) 0.45, 90% interval 0.35 to 0.59. The upper end of that interval is the gene's LOEUF score, 0.59, which puts it in group 2 of 6, group 1 being the genes least tolerant of losing a copy. Missense variants: 827 observed, 1,005.1 expected, observed/expected ratio (o/e) 0.82, 90% interval 0.78 to 0.87. Synonymous variants: 392 observed, 397.15 expected, observed/expected ratio (o/e) 0.99, 90% interval 0.91 to 1.07.
Homologues: Orthologues: chimpanzee ACSBG1 (99% identical), macaque ACSBG1 (97% identical), rat Acsbg1 (86% identical), mouse Acsbg1 (86% identical), rabbit ACSBG1 (86% identical), dog ACSBG1 (85% identical), guinea pig ACSBG1 (83% identical), pig ACSBG1 (82% identical), tropical clawed frog acsbg1 (60% identical), zebrafish acsbg1 (57% identical), Drosophila melanogaster bgm (36% identical), Drosophila melanogaster hll (35% identical), and 22 more. Paralogues in human: ACSBG2 (45% identical), ACSL1 (23% identical), ACSL5 (23% identical), ACSL6 (23% identical), ACSL3 (21% identical), ACSL4 (19% identical), SLC27A6 (15% identical), SLC27A2 (15% identical), SLC27A3 (15% identical), SLC27A4 (14% identical), SLC27A5 (14% identical), SLC27A1 (13% identical).
Diseases named in the same sentence as ACSBG1 in open-access papers:
ACSBG1 is named in the same sentence as 26 diseases in open-access papers, as found by Europe PMC text mining. Sharing a sentence is not in itself a finding about the gene and the disease. The quoted sentences say what the papers report.
breast carcinoma (3 papers, 2017 to 2025). "Considering the reported correlation between ACSBG1 and breast cancer progression, a comprehensive investigation was conducted to determine the potential contribution of ACSBG1 to ESCC progression." (PMID 40448098, 2025).
X-linked adrenoleukodystrophy (3 papers, 2016 to 2024). X-linked adrenoleukodystrophy (X-ALD) is a peroxisomal disorder resulting in cerebral demyelination, axonal dysfunction in the spinal cord leading to spastic paraplegia, adrenal insufficiency and in some cases testicular insufficiency. "Several studies suggest that ACSBG1 may be involved in the biochemical pathology of X-linked adrenoleukodystrophy (X-ALD)." (PMID 27857161, 2016). "Originally discovered in the fruit fly brain, ACSBG1 attracted attention for its potential implication in X-linked adrenoleukodystrophy (XALD) pathogenesis." (PMID 38948805, 2024). "Fruit fly mutants lacking ACSBG1 exhibited neurodegeneration and had elevated levels of very long-chain fatty acids (VLCFA), characteristics of human X-linked adrenoleukodystrophy (XALD)." (PMID 39451204, 2024).
depression (2 papers, 2024). "Thus, reduced ACSBG1 expression could be associated with improvements in cardiovascular disease, reduced complications of diabetes and a lowered risk for depression." (PMID 39451204, 2024). "Thus, reduced ACSBG1 expression could be associated with improvement in cardiovascular disease, reduced complications of diabetes and lowered risk for depression." (PMID 38948805, 2024).
Obesity (2 papers, 2021 to 2025). Accumulation of substantial excess body fat. "Acsbg1 converts long-chain fatty acids into ATP and phospholipids, triglycerides, and cholesterol esters, and has been linked to obesity-driven tumor progression." (PMID 40941077, 2025). "Accordingly, in vivo experiments have confirmed that obesity can affect the function and number of CD8+ immune cells through the related STAT3 pathway, metabolite GATM and ACSBG1 gene." (PMID 34901155, 2021).
acne (1 paper, 2020). An inflammatory process of the sebaceous glands which is characterized by comedones, nodules, papules and/or pustules on the skin. "There were consistently 0 upregulated and 2 downregulated genes, including ACSBG1 and BCAT2, among GSE10432 (SEB-1 sebocytes incubated with isotretinoin for 72 hours), GSE10433 (acne patients treated with isotretinoin for 1 week), and GSE11792 (acne patients treated with isotretinoin for 8 weeks)." (PMID 32685503, 2020).
atopic dermatitis (1 paper, 2018). "Some of lipid metabolic genes discovered in our analysis were also reported as declined genes in patients with psoriatic (ACSBG1, ALOX15B, ELOVL3, FADS1, FADS2, and THRSP) or atopic dermatitis (CYP4F8, ELOVL3, FADS1, FADS2, FAR2, and HAO2)." (PMID 30021930, 2018).
behavioural disorders (1 paper, 2017). "Moreover, CPT1B has been recently associated with behavioural disorders characterizing post-traumatic stress both in human and rodent models, and ACSBG1 participate in myelinogenesis." (PMID 29020091, 2017).
lung carcinoma (1 paper, 2021). "Multivariate Cox regression analysis of gender, age, stage, cancer type, GAPDHS, ACSBG1, and CYP4A11 found that older (>60 years) age, highly expressed GAPDHS, low expressed ACSBG1, and low expressed CYP4A11 were high-risk factors for lung cancer prognosis." (PMID 34970420, 2021). "(ii) The survival prognosis of lung cancer patients was better in the high expression group than low expression group of ACSBG1 (p < 0.05)." (PMID 34970420, 2021). "In lung cancer tissue, high expression of GAPDHS, low expressions of ACSBG1, CYP4A11, mutated ACOX3, and old age predict a poor prognosis." (PMID 34970420, 2021). "The advanced age, high expression of GAPDHS, low expressions of ACSBG1 and CYP4A11, and ACOX3 mutation were biomarkers of poor prognosis in lung cancers." (PMID 34970420, 2021). "High expression of GAPDHS, low expression of ACSBG1, low expression of CYP4A11, mutated ACOX3, and old age predict a poor prognosis of lung cancer." (PMID 34970420, 2021). "Further verification in the independent data set GSE21933 showed that ACSBG1 was a significantly low expression in the lung cancer group, and LogFC was 0.81 (p < 0.05)." (PMID 34970420, 2021). "Three survival-related differentially expressed MMRGs were found, including GAPDHS, ACSBG1, and CYP4A11, in lung cancer." (PMID 34970420, 2021). "Survival analysis of 43 differentially expressed MMRGs in lung cancer found that 3 differentially expressed MMRGs (GAPDHS, ACSBG1, and CYP4A11) had survival significance." (PMID 34970420, 2021). "Our study found the significantly high expression of GAPDHS, low expression of ACSBG1, and low expression of CYP4A11 in lung cancer tissues predicted poor prognosis for survival, whatever with single-factor and multifactor survival analytical strategies." (PMID 34970420, 2021).
ovarian carcinoma (1 paper, 2016). A malignant neoplasm originating from the surface ovarian epithelium. "Whereas, our findings confirm a significant association in Lebanese BC patients between the expression levels of FOSL1, Acyl-CoA synthetase bubblegum family member 1 (ACSBG1), and Chromosome 21 open reading frame 37 (C21orf37) genes with ER/PR expression and family history of ovarian cancer." (PMID 27857161, 2016).
Parkinson disease (1 paper, 2025). A progressive degenerative disorder of the central nervous system characterized by loss of dopamine producing neurons in the substantia nigra and the presence of Lewy bodies in the substantia nigra and locus coeruleus. "The GSEA results showed that Acsbg1 was enriched to 13 KEGG pathways (lysosome, oxidative phosphorylation, and Parkinsons disease, etc.), and the Etnppl was enriched to 14 pathways (lysosome, proteasome, and ribosome, etc.)." (PMID 40182633, 2025).
tumor (7 papers, 2014 to 2025). "Notably, ESCC cell proliferation was inhibited after knockdown of ACSBG1, and the opposite was observed after overexpression of ACSBG1, which was further verified by the reduction of tumor size in the nude mouse xenograft model." (PMID 40448098, 2025). "The present study identified circSLC22A3 as a new tumor suppressor that inhibited ESCC progression through both the circSLC22A3/ miR-19b-3p/ TRAK2 and circSLC22A3/ IGF2BP1/ ACSBG1 axes." (PMID 40448098, 2025). "However, the expressions of ACSBG1 and CYP4A11 in four tumor stages (stages I, II, III, and IV) were statistically significant difference, respectively (p < 0.05)." (PMID 34970420, 2021).
cancer (4 papers, 2017 to 2025). A tumor composed of atypical neoplastic, often pleomorphic cells that invade other tissues. "In both ESCC tissues and cells, there was a significantly higher expression of ACSBG1, suggesting that it played a role in cancer development." (PMID 40448098, 2025).
cardiovascular disease (3 papers, 2024 to 2025). "Studies have shown that Acsbg1 affects FA β-oxidation and disrupts energy metabolism, leading to cardiac metabolic disorders and increased risk of cardiovascular diseases." (PMID 40182633, 2025).
metabolic disease (2 papers, 2024). A congenital disorder (due to inherited enzyme abnormality) or acquired (due to failure of a metabolically important organ) disorder resulting from an abnormal metabolic process. "Further research is needed to fully elucidate the function of ACSBG1 and its implications in metabolic diseases." (PMID 38948805, 2024).
diseases of the central nervous system (1 paper, 2025). "These include genes involved in neurodegeneration (EIF5), diseases of the central nervous system (IPO13, ST3GAL3), tobacco addiction (CHRNB4, PSMA4), fatty acid metabolism (ACSBG1), and skin conditions (HYI, ELOVL1)." (PMID 40074595, 2025).
ACSBG1 also shares sentences with these, for which no sentence is quoted: diabetes (2 papers); infection (2); adrenoleukodystrophy (1); fungal infection (1); lung adenocarcinoma (1); lung squamous cell carcinomas (1); lymphoma (1); Mitchell syndrome (1); squamous carcinoma (1); virus infection (1); vitiligo (1).